PTH (parathyroid hormone)
Diseases named in the same sentence as PTH in open-access papers (continued):
Sharing a sentence is not in itself a finding about the gene and the disease.
hypoparathyroidism (466 papers, 2006 to 2026). Hypoparathyroidism is an endocrine disorder in which the parathyroid glands in the neck do not produce enough parathyroid hormone (PTH). "PURPOSE: Hypoparathyroidism (HPT) is an endocrine disease caused by insufficient levels of parathyroid hormone (PTH)." (PMID 41642436, 2026). "Background/Objectives: Hypoparathyroidism (HPT) is a disorder caused by the insufficient production of parathyroid hormone (PTH)." (PMID 41891992, 2026). "Measuring PTH levels at 6 hours postthyroidectomy is an accurate method for predicting which patients are at risk of developing transient and/or permanent hypoparathyroidism." (PMID 40671592, 2026). "PTH+ levels after thyroid surgery are generally used to detect patients at risk of developing postoperative hypoparathyroidism." (PMID 40671592, 2026). "Hypoparathyroidism is a frequent complication following thyroidectomy, characterized by a severe deficiency of parathyroid hormone (PTH)." (PMID 40969367, 2025). "This study shows that intraoperative topical irrigation with papaverine significantly reduces the risk of early hypoparathyroidism (HP) after total thyroidectomy and helps restore PTH levels." (PMID 41356014, 2025). "TransCon PTH treatment was associated with sustained improvements in clinical outcomes as well as disease-related symptoms and the impact of hypoparathyroidism on physical functioning and daily life." (PMID 39376010, 2025). "Applying papaverine directly during surgery effectively lowers the risk of early hypoparathyroidism after total thyroidectomy while promoting faster PTH recovery." (PMID 41356014, 2025). "Hypomagnesemia impairs PTH secretion and action, leading to functional hypoparathyroidism and bone loss." (PMID 40979723, 2025). "The dysfunction observed ranges from inappropriate elevation of PTH levels to hypoparathyroidism, leading to rapid bone density loss and an increased fracture risk." (PMID 41295288, 2025). "We observed that preoperative high glucose levels are a risk factor for both postoperative hypoparathyroidism and significant PTH reduction." (PMID 40969367, 2025). "Hypoparathyroidism is an endocrine disease caused by insufficient levels of parathyroid hormone (PTH)." (PMID 39376010, 2025). "Hypoparathyroidism (HypoPT) is a rare syndrome caused by insufficient parathyroid hormone (PTH) secretion." (PMID 40713713, 2025). "Postsurgical hypoparathyroidism is one of the most frequent causes of hypocalcemia and low serum levels of parathyroid hormone." (PMID 40346324, 2025). "Here, we show that PTH1R exists as a monomer in live cells under both basal and ligand-bound conditions, even in the presence of a dimeric form of the PTH mutant, PTHR25C (residue 25 of PTH), which is linked with hypoparathyroidism." (PMID 41203134, 2025). "In exploratory analysis, treatment with PTH analogues was associated with a lower risk of incident cardiovascular disease compared to conventional treatment in patients with hypoparathyroidism." (PMID 40869557, 2025). "Hypoparathyroidism is a complex disease which does not only refer to a deficiency of parathyroid hormone; consecutively also the level of the active form of vitamin D is reduced, since the presence of a sufficient amount of PTH is required for its synthesis." (PMID 39636417, 2024). "Hypoparathyroidism is an uncommon hormonal deficiency condition characterized by low blood calcium levels, elevated phosphorus levels, and insufficient parathyroid hormone (PTH)." (PMID 38186939, 2024). "Postoperative hypoparathyroidism is a common complication following thyroidectomy, characterized by a deficiency in PTH, which is crucial for regulating calcium and phosphate levels in the body." (PMID 39258042, 2024). "(i)Parathyroid hormone secretion is under feedback control by the calcium-sensingreceptor, which responds to a diverse array of activating ligands.(ii) Postoperative hypoparathyroidism arises from a secretory deficiencyof the parathyroid glands." (PMID 39022353, 2024).
hypoparathyroidism (continued). "The findings will provide insights, from the patient perspective, into the impacts of TransCon PTH on physical and cognitive symptoms associated with hypoparathyroidism, as well as broader impacts on patient functioning and QOL." (PMID 39136801, 2024). "So far, only 11 PTH mutations have been described as causes of familial isolated hypoparathyroidism (FIH)." (PMID 39435356, 2024). "For zero, one, two, three, and four identified PGs, the risk of hypoparathyroidism in one-hour parathyroid hormone level postoperative was 6.6%, 7.3%, 34.4%, 34.4%, and 17.2% respectively." (PMID 38107216, 2023). "This study shows that patients with lower PTH levels (less than 1.2 pg/ml) within three days after surgery had a higher risk of permanent hypoparathyroidism, similar to previous studies." (PMID 37545843, 2023). "Low PTH concentration predisposed to a higher incidence of hypoparathyroidism (p = 0.055, OR = 0.98, OR − 95% CI-0.96, OR + 95% CI-1.00)." (PMID 37626794, 2023). "Low preoperative PTH levels were associated with a higher incidence of hypoparathyroidism (p = 0.055, OR = 0.9)." (PMID 37626794, 2023). "Intraoperative number of identified PGs was zero, one, two, three, and four and the risk of hypoparathyroidism in one hour PTH level was 6.6%, 7.3%, 34.4%, 34.4%, and 17.2% respectively." (PMID 38107216, 2023). "Other than post-surgical hypoparathyroidism, idiopathic hypoparathyroidism was most frequent, even though a number of genetic causes of impaired PTH secretion have been identified." (PMID 36123043, 2023). "Hypoparathyroidism is a rare condition caused by undetectable or inappropriately low secretion of parathyroid hormone (PTH) that is insufficient for maintaining the plasma calcium concentration (PCa) within the normal range." (PMID 34939939, 2022). "Patients with 22q11.2DS have a long-term risk of overt hypoparathyroidism at any age, even in those with some parathyroid hormone reserve." (PMID 35432203, 2022). "Hypoparathyroidism is a medical condition caused by the loss of PTH, and it frequently occurs on damaged or removed parathyroid glands as an accidental excision during thyroid surgeries." (PMID 35203648, 2022). "Hypoparathyroidism is a rare condition caused by defective release of parathyroid hormone (PTH), resulting in impaired mineral metabolism." (PMID 35485213, 2022). "The risk of permanent hypoparathyroidism was < 1% for POD1 PTH levels ≥ 15 pg/ml; 5.4% for levels 10–14 pg/ml; and 19.8% for levels < 10 pg/ml." (PMID 35247092, 2022). "Future studies should ideally address specific aspects, such as more standardized analyses of the effects of PTH replacement therapy on QoL and the risk of bone adverse events in hypoparathyroidism." (PMID 35485213, 2022). "Among patients with POD1 PTH levels 10–14 pg/ml, the risk of permanent hypoparathyroidism was 5.4%, while among patients with POD1 PTH levels 15–19 pg/ml and ≥ 20 pg/ml, the risk was 1.6% and 0.3%, respectively." (PMID 35247092, 2022). "The main risk factors associated with long-term postoperative hypoparathyroidism are combined with lymph node dissection (P = 0.011, OR 1.594), maximum thyroid diameter (P = 0.032, OR 1.254), and PTH on the first day after surgery (P < 0.001, OR 1.199)." (PMID 34095206, 2021). "Measuring PTH levels during the postoperative 4–6 h can allow early discharge of patients at low risk of developing hypoparathyroidism and the early treatment of high-risk patients." (PMID 34088943, 2021). "Familial hypoparathyroidism (autosomal recessive) can result from parathyroid hormone loss-of-function mutations (encoded on chromosome 3p21) which can also occur resulting in poor or absent hormonal signaling." (PMID 35299844, 2021). "Combined lymphadenectomy, the maximum diameter of the thyroid gland, and PTH on the first day after surgery (d1PTH) were associated with long-term hypoparathyroidism (P < 0.05)." (PMID 34095206, 2021).
hypoparathyroidism (continued). "Chemical analysis of our patient showing decreased calcium level associated with increased phosphorus and low PTH values, and suggesting hypoparathyroidism (HPTH)." (PMID 35082750, 2021). "The wide variation of postoperative hypoparathyroidism incidence is caused partly by the discrepancies in the definition of hypoparathyroidism and the detection time of serum PTH." (PMID 34956363, 2021). "Hypoparathyroidism is associated with reduced production of parathyroid hormone (PTH), resulting in an imbalance between calcium and phosphorus." (PMID 34093855, 2021). "Further diagnostic workup revealed low levels of parathyroid hormone, thereby unmasking a diagnosis of idiopathic primary hypoparathyroidism presenting as late-onset hypocalcemic fits." (PMID 33062471, 2020). "The clinical presentation of hypoparathyroidism can be also sustained by PTH resistance, mostly due to inactivating mutations of the GNAS1 gene, a disorder known as pseudohypoparathyroidism." (PMID 32751307, 2020). "Expectedly in this study, an association between low serum calcium with low serum PTH in patients with hypoparathyroidism was found." (PMID 33198660, 2020). "Hypoparathyroidism is an endocrine disorder caused by insufficient parathormone (PTH) secretion or, very rarely, by PTH receptor resistance." (PMID 33033457, 2020). "The mutated receptor is expressed in the parathyroid glands causing suppression of PTH synthesis and secretion at normal ionized calcium levels leading to hypoparathyroidism." (PMID 30540559, 2019). "Hypoparathyroidism is an endocrine deficiency that originates from low parathyroid hormone (PTH) levels." (PMID 30093637, 2018). "In thalassemia major patients, iron deposition (secondary to chronic anemia) in the parathyroid gland causes hypoparathyroidism and it suppresses the parathyroid hormone secretion." (PMID 24174700, 2013). "When serum levels reach >32 ng/mL, parathyroid hormone (PTH) levels become stable and reduce the risk of secondary hypoparathyroidism, which is commonly associated with low vitamin D status." (PMID 23760056, 2013). "Hypoparathyroidism is an inherited or acquired deficiency of the parathyroid hormone (PTH) or its action." (PMID 22251708, 2012). "During followup, the patient was investigated for associated polyendocrinopathy and found to have hypoparathyroidism and adrenal insufficiency with markedly low parathyroid hormone (PTH) despite impaired renal function." (PMID 21197407, 2010). "In addition to CT imaging, biochemical assessment of serum calcium, phosphate, parathyroid hormone, and vitamin D levels is essential to determine the underlying etiology—particularly in cases involving hypoparathyroidism." (PMID 41403967, 2026). "The persistent benefit in PTH recovery rates within the papaverine group from postoperative days 3 to 30 suggests it may help reduce the risk of permanent hypoparathyroidism; however, longer-term studies are needed to confirm this." (PMID 41356014, 2025). "A meta-analysis from 2024 reported that only preoperative levels of calcium constitute a risk factor for hypoparathyroidism, whereas preoperative parathyroid hormone levels could be a protective factor." (PMID 40648792, 2025). "A potential risk accompanying lower 12-month PTH values is relative hypoparathyroidism." (PMID 40670910, 2025). "Moreover, the dimeric form of the PTH mutant PTHR25C (encountered in idiopathic hypoparathyroidism), which restores the structural and signaling defects caused by the PTH mutation, also operates through a PTH1R monomer." (PMID 41203134, 2025). "Therefore, in this study, we introduced a new threshold method based on the decline rates of PTH levels to investigate the key factors influencing parathyroid function, and identifying the potential risk factors for hypoparathyroidism after thyroidectomy." (PMID 40969367, 2025).
hypoparathyroidism (continued). "Importantly, patients with normal PTH levels within 24 h of surgery had a very low risk of developing permanent hypoparathyroidism." (PMID 41229353, 2025). "SARS-CoV-2 may disrupt the balance of phosphate, calcium, and parathyroid hormone and has been identified as a potential cause of hypoparathyroidism." (PMID 39066437, 2024). "Additionally, the study identified potential risk factors for postoperative hypoparathyroidism, revealing that the surgical procedure (P = 0.0002) and PTH level (P < 0.001) were significantly associated with postoperative hypoparathyroidism." (PMID 40071247, 2024). "Hypoparathyroidism is significantly associated with older age, the mean received blood transfusion, total transfused blood per year, splenomegaly, hepatomegaly, and chelation regimen, while splenectomy is an independent risk factor for low PTH." (PMID 39233987, 2024). "Venous blood flow is affected and some of the parathyroid glands become edematous, ischemic and necrotic, causing great uncertainty in parathyroid function, which may cause low parathyroid hormone levels and permanent hypoparathyroidism." (PMID 37441504, 2023). "The aim was to investigate whether the use of autofluorescence to detect the parathyroid glands during total thyroidectomy reduced the risk of postoperative hypoparathyroidism, defined by a low level of parathyroid hormone (PTH) on the day after surgery." (PMID 37758507, 2023). "Additionally, although improved kidney function can cause hypoparathyroidism, the PTH secreted from remnant PTGs can avoid this problem." (PMID 37152972, 2023). "Moreover, a postoperative PTH level of <5 pg/mL significantly increased the risk for definitive hypoparathyroidism (OR = 23.2 (95% CI 2.45–208.43, p < 0.0001)." (PMID 36902740, 2023). "A previously unknown role of FAM111A in the regulation of PTH has been speculated, which would cause hypoparathyroidism and compromise normal skeletal development." (PMID 35205306, 2022). "Of interest, PTH therapy of hypoparathyroidism for 8 years has been associated with a stable kidney function, whereas a decline in kidney function often occurs if patients are treated with conventional therapy in terms of active vitamin D and calcium supplements." (PMID 34991581, 2022). "Notably, most cases of hypoparathyroidism in neonates are due to maternal hyperparathyroidism, which suppresses the fetal parathyroid hormone levels and thus causes seizures." (PMID 33062471, 2020). "A low serum albumin-adjusted calcium <2.0 mmol/L or <8 mg/dL in the presence of a low PTH <15 pg/mL is associated with a high risk of permanent hypoparathyroidism and requires appropriate supplementation with calcium and active vitamin D metabolites and follow-up." (PMID 30540559, 2019). "It maintains calcium homeostasis by directly regulating bone remodeling and renal excretion, and indirectly regulating the production of 1,25-dihydroxyvitamin D. Deficiency of PTH leads to hypoparathyroidism, a metabolic disorder in which the diagnosis is confirmed by the occurrence of hypocalcemia." (PMID 29791658, 2018). "Hypoparathyroidism is a deficiency of the parathyroid hormone (PTH) in the body." (PMID 30093637, 2018). "Hypoparathyroidism is an endocrine disease that results from parathyroid hormone (PTH) deficiency or any resistance to its hormonal function, and manifestations of this disease mainly include hypocalcemia, hyperphosphatemia, and abnormal PTH serum level." (PMID 27957632, 2017). "Hypoparathyroidism (HP) is a metabolic disorder caused either by deficient or absent production of the parathyroid hormone (PTH) by the parathyroid glands or by resistance to PTH in its target tissues (a condition called pseudo-HP)." (PMID 27901178, 2016). "There is some indication that hypoparathyroidism (low serum PTH and calcium levels) may be associated with poorer cognitive function too." (PMID 26010883, 2015).
hypoparathyroidism (continued). "This drop in postnatal SCa has been associated with hypoparathyroidism, end-organ unresponsiveness to parathyroid hormone, abnormalities of vitamin D metabolism and to hyperphosphatemia, hypomagnesemia, and hypercalcitoninemia which evolve by 12-24 hours of age." (PMID 24072092, 2013). "Given that both hyper- and hypoparathyroidism are associated with increased risk of bone fracture, we speculated that caffeine might affect bone quality through modulation of PTH secretion." (PMID 23788688, 2013). "Thus, they are not hypoparathyroid, which would be associated with undetectable serum PTH concentrations, or pseudo-hypoparathyroid, which would be associated with elevated serum PTH concentrations." (PMID 18446382, 2009). "Recent studies have considered the possibility that the functionally defective PTH mutant with Arg-to-Cys mutation at position 25 (PTHR25C) found in patients with idiopathic hypoparathyroidism could act as a covalent homodimer because of a potential disulfide bond between C25 residues." (PMID 41203134, 2025). "The findings indicate that TransCon PTH improved participants’ physical and cognitive hypoparathyroidism symptoms in meaningful ways, while reducing the daily treatment burden, e.g., fewer oral medications needed, associated with conventional therapy for hypoparathyroidism." (PMID 39136801, 2024). "In this study, we evaluated the risk factors for low levels of PTH after surgery for thyroid cancer to identify the patient and surgical related factors that could have a significant correlation with the development of hypoparathyroidism." (PMID 34575224, 2021). "PTH secretion may also be deregulated by anti-CaSR antibodies activating the CaSR receptor by mimicking calcium and inhibiting the secretion of this hormone; this is a rare cause of hypoparathyroidism." (PMID 29694629, 2018). "This requires a more precise diagnosis of permanent hypoparathyroidism and more accurate postsurgical PTH cutoff points than those determined in previous retrospective studies." (PMID 40671592, 2026). "The secondary objective is to evaluate the predictive capability of this early PTH measurement for diagnosing a well-defined 1-year mark of permanent hypoparathyroidism." (PMID 40671592, 2026). "The supplementation of activated vitamin D and calcium is provided to treat postoperative hypoparathyroidism, based on the levels of postoperative PTH." (PMID 41319240, 2026). "PTH levels of < 15 pg/mL, measured at least 20 min after thyroidectomy, can assist in predicting potentially clinically significant hypoparathyroidism and early substitution therapy." (PMID 41319240, 2026). "Currently, there is limited evidence regarding the utility of postoperative PTH as a predictor of long-term permanent hypoparathyroidism." (PMID 40671592, 2026). "To examine the PTH-independent effects of CaSR inhibition on renal calcium handling, we administered a calcilytic (CaSR antagonist) to individuals with post-surgical hypoparathyroidism (PSH)." (PMID 42183375, 2026). "Statement 13: Short-term postoperative follow-up data necessary for assessing prevalence of early postoperative hypoparathyroidism should include serum PTH levels on the day of surgery or POD1 (based on surgeon/institutional protocol)." (PMID 41229353, 2025). "This case illustrates that post-PTX oversuppression of PTH, in combination with heavy calcium-phosphate load, and possibly vitamin K deficiency, can contribute to CUA even in the context of surgical hypoparathyroidism." (PMID 41473615, 2025). "This dose and route of administration was used as it has been previously shown to increase PTH both in WT rats and a rat postsurgical hypoparathyroidism model." (PMID 40086735, 2025). "While PTH replacement medication, such as teriparatide, is usually considered safe and effective for treating hypoparathyroidism, it can have side effects (most notably, hypercalcemia)." (PMID 40806191, 2025).